ATP7A (ATPase copper transporting alpha)
Diseases named in the same sentence as ATP7A in open-access papers (continued):
Sharing a sentence is not in itself a finding about the gene and the disease.
tumor (continued). "The copper-transporting P-type ATPases ATP7A and ATP7B are both expressed in the cochlea-ATP7A localizes predominantly to pillar cells of the organ of Corti, whereas ATP7B is found in hair cells-and have been implicated in tumor resistance to platinum drugs." (PMID 41169615, 2025). "Additionally, the activity and movement of ATP7A/B enable tumour cells to detoxify certain drugs used in the chemotherapy of various solid tumours." (PMID 38999951, 2024). "Furthermore, it has been reported that combined treatment with DSF and cisplatin can alter the cellular localization of ATP7A, thereby increasing the drug concentration within tumor cells, promoting apoptosis, and inhibiting tumor growth." (PMID 38918694, 2024). "Thus, LOX activities are silenced by the ATP7A gene to inhibit tumour growth and metastatic potential in cancer cell lines." (PMID 37049685, 2023). "We also investigated the relationship between ATP7A and tumor related immune cells and found that ATP7A is positively correlated with cancer associated fibroblast, Tregs, macrophages M1, macrophages M2, CD4+ T cells, CD8+ T cells and NK cells, but negatively correlated with T cell gamma delta." (PMID 37885090, 2023). "In tumor cell-enriched region, higher expression of SLC31A1 (P = 0.001) was associated with worse prognosis of NPC patients, while the opposite was true for LIPT2 (P = 0.012) and ATP7A (P = 0.011)." (PMID 36618352, 2022). "Indeed, increased expression of the Golgi-localized Cu-transporting ATPases, ATP7A and ATP7B, have been associated to tumor aggressiveness as well as chemo-resistance." (PMID 33015030, 2020). "To validate the involvement of ATP7A in KRAS-dependent tumor growth, we performed soft agar assays using KRAS IEC-6 and KRAS-mutated CRC cells, and found that shRNA-mediated ATP7A knockdown reduced anchorage-independent growth." (PMID 32709883, 2020). "ATP7A regulates the intracellular Cu levels and tumor growth in KRAS-transformed cells." (PMID 32709883, 2020). "However, the potential of autophagy suppressors to promote Pt-toxicity in tumor cells with elevated ATP7A/B expression has yet to be tested." (PMID 31540259, 2019). "Furthermore, ATP7A/B activity and trafficking allow tumor cells to detoxify platinum (Pt)-based drugs (like cisplatin), which are used for the chemotherapy of different solid tumors." (PMID 31540259, 2019). "Another important issue that has to be taken into account is that suppression of either ATP7A or ATP7B, which is desirable in tumors, might cause significant side effects in extra-tumor tissues." (PMID 31540259, 2019). "This suggested that ATP7A might be involved in transformation of a normal differentiated cell to a malignant tumor cell." (PMID 22304828, 2012). "Besides the loss of LOX metallization, the accumulation of copper and ROS may also play a role in the inhibitory impact of ATP7A, suppressing tumor growth and metastasis." (PMID 39676279, 2024). "Targeting ATP7A/ATP7B could increase tumor cell sensitivity to platinum drugs." (PMID 38918694, 2024). "However, the efficacy of Pt-based therapy might be seriously compromised by the development of resistance mechanisms, which include ATP7A/B-mediated Pt excretion from tumor cells." (PMID 31540259, 2019). "Notably, exosomes from tumor cells have been shown to contain both ATP7A and ATP7B." (PMID 31540259, 2019). "ATOX1 mediates the metastasis of breast cancer cells through coordinated copper transport along the ATP7A-LOX axis, making the levels of ATOX1 in tumor cells a potential predictive marker of metastatic potential and a biomarker for copper depletion therapy." (PMID 40341098, 2025). "Conversely, silencing ATOX1 or inhibiting ATP7A activity can reduce LOX function and inhibit tumor cell proliferation and migration." (PMID 39691393, 2024). "Specifically, genes such as LIPT1, ATP7A, LIAS, DBT, and PDHB were found to be significantly downregulated in the tumor tissue." (PMID 38898987, 2024).
tumor (continued). "Many genetic and biochemical studies have also shown that the copper transporter proteins ATP7A and ATP7B can promote platinum drug resistance by controlling their uptake and export from tumor cells." (PMID 39539553, 2024). "Gene expression profiling showed that SLC31A1, LIPT2, CDKN2A, and GCSH expression was increased in tumor tissues, while NFE2L2, NLRP3, ATP7A, DLD, MTF1, and DLST expression was decreased in tumor tissues compared with normal tissues." (PMID 37065485, 2023). "The under-expression of SLC22A1, SLC22A2, SLC47A1, CTR1, and CTR2 leads to reduce uptake of cisplatin whereas the upregulation of ATP7A, ATP7B, MRP1, MRP2, and MRP4 are responsible for increased efflux of cisplatin out of the tumor cell." (PMID 36715825, 2023). "In conclusion, targeting Copper-transporting ATPases,ATP7A or ATP7B,has broad application space in overcoming the resistance of tumor cells to platinum drugs." (PMID 36925927, 2023). "In the tumor cell region, the patients with higher expression of LIPT2 and ATP7A had the better prognosis; while the higher the expression of SLC31A1, the worse the prognosis of NPC patients." (PMID 36618352, 2022). "Cu transporter-related genes including ATP7A, SLC31A1, and TCA-related genes including DBT, DLST, and DLAT are differentially expressed between normal and tumor samples." (PMID 36438201, 2022). "The results showed that, in tumor samples, ATP7B, PDHA1, and SLC31A1 were significantly upregulated compared with normal tissues, whereas ATP7A, DLST, GCSH, LIAS, and LIPT1 were significantly downregulated." (PMID 36567939, 2022). "ATP7A (P = 0.008), COA6 (P = 0.016), TMEM199 (P = 0.024) and FDX1 (P = 0.004) expression were significantly related to tumor stage (T classification)." (PMID 36313717, 2022). "A recent study indicated that ATP7A plays essential roles in loading lysyl oxidase (LOX) and LOX-like (LOXL) proteins, which have well-documented roles in tumor metastasis." (PMID 32709883, 2020). "By harboring the Cu-transporting ATPases ATP7A and ATP7B, the Golgi regulates the supply of Cu to several oncogenic metalloenzymes and the overall availability of Cu in tumor cells." (PMID 31540259, 2019). "In this review, we discuss how the ability of the Golgi resident transporters ATP7A and ATP7B to handle Cu and Pt enables malignant cells to protect themselves from cisplatin-mediated death and to promote tumor growth and invasion." (PMID 31540259, 2019). "In addition, ATP7A and ATP7B are also involved in regulating the transport of platinum-based drugs within tumor cells." (PMID 40013141, 2025). "Besides, ATP7A and ATP7B can interact with platinum drugs and pump them across membranes, contributing to the resistance of tumor cells to platinum-based cancer treatments." (PMID 38918694, 2024). "Besides Cu transport, ATP7A and ATP7B can interact with platinum drugs and pump them across membranes, contributing to the resistance of tumor cells to platinum-based cancer treatments." (PMID 38918694, 2024). "We found that FDX1, LIPT1, DLAT, PDHA1, PDHB, DLST, and ATP7A were significantly differentially expressed in tumor and nontumor tissues, with the standard of p < 0.05." (PMID 36975441, 2023). "ATP7A may suppress tumor cell growth and migration by inhibiting the activity of LOX.ATP7A may promote angiogenesis by combining with VEGFR2.ATP7A or ATP7B can bind to platinum drugs to expel it from cancer cells, producing chemotherapy drug resistance." (PMID 36925927, 2023). "Specifically, we encapsulated siRNA targeting ATP7A using DANs and confirmed that DAN-siATP7A could be effectively enriched in tumor tissue and downregulate the target gene." (PMID 35265524, 2022). "There was no ATP7A expression difference between the adjacent normal tissue and tumor tissue, and the bioinformatic analysis displayed that the ATP7A expression was not related to the TNM stage." (PMID 35265524, 2022).
tumor (continued). "Additionally, the same Golgi-resident transporters ATP7A and ATP7B are also capable of pumping Pt across membranes rendering the tumor cells resistant to Pt-based cancer therapy." (PMID 31540259, 2019). "Consistent with previously reported outcomes, approximately one-third (n = 10) of patients showed marked pathological response, but irrespective of ATP7A expression in pre-treatment tumour tissue." (PMID 31673101, 2019). "Therefore, the presence of ATP7A and ATP7B in these structures suggests that both proteins traffic to LEs/lysosomes in Pt-resistant tumor cells." (PMID 31540259, 2019). "Indeed, silencing of ATP7A was able to inhibit LOX activity and, as a result, to suppress LOX-dependent mechanisms of tumor progression." (PMID 31540259, 2019). "This scenario favors the idea that sequestration of cisplatin by MBSs of ATP7A/B, rather than active transport of Pt across the membrane, provides the key contribution to the resistance of tumor cells to cisplatin." (PMID 31540259, 2019). "ATP7A was detected in cytoplasmic staining of tumor cells in 37 of 89 (41.6%) tumors but not in adjacent stroma nor normal lung tissue." (PMID 22304828, 2012). "Additionally, ATP7A and ATP7B also produce a marked effect in tumor progression." (PMID 36925927, 2023). "This review summarizes current data on the role of ATP7A/B in the regulation of Cu and Pt metabolism in malignant cells and outlines questions and challenges that should be addressed to understand how ATP7A and ATP7B trafficking mechanisms might be targeted to counteract tumor development." (PMID 31540259, 2019). "ATP7A expression in post-NAC tumours could not be evaluated in the ten patients due to no or little residual tumour lesion." (PMID 31673101, 2019). "Moderate-to-strong ATP7A expression (G2 or G3) was observed in over 70% of pre-treatment tumours (left and 2j, left), although we could not evaluate subcellular localisation of ATP7A by using IHC unfortunately." (PMID 31673101, 2019). "Finally, despite a significant contribution to tumor development and drug resistance, ATP7A and B do not work alone to trigger oncogenic processes." (PMID 31540259, 2019). "Given that tumor cells are metabolized through aerobic fermentation, ROS present in the non-immune TME of AOC upregulates the expression of ATP7A and ATP7B by activating the Nrf2 signaling pathway." (PMID 40013141, 2025). "Among these genes, ATP7A and NFE2L2 did not display statistically significant differences in their expression levels between the tumor and normal samples." (PMID 38041690, 2024). "However, the IHC results of SLC25A3 protein between normal and HCC tumor tissues were not existed in HPA, besides the obvious trend differences of ATP7A and ATP6AP1 expression in HCC patients were difficult to show in the HPA database." (PMID 36313717, 2022).
cancer (62 papers, 2012 to 2025). A tumor composed of atypical neoplastic, often pleomorphic cells that invade other tissues. "ATP7A regulates copper homeostasis, and its disruption causes copper imbalance, leading to oxidative stress and cancer progression." (PMID 40236776, 2025). "The single-nucleotide variation (SNV) analysis revealed that ATP7B and ATP7A were the two most frequently mutated copper metabolism-related cell death genes in cancer." (PMID 36276096, 2022). "Here we describe a novel TAp73 target, ATP7A a member of a large family of P-type ATPases implicated in human neurogenerative conditions and cancer chemoresistance." (PMID 30530920, 2018). "ATP7A was found to be upregulated in multiple cancers and associated with cancer progression." (PMID 36568224, 2022). "ATP7B and ATP7A were the two most frequently mutated copper cell death genes in cancer." (PMID 36276096, 2022). "The TAp73/ATP7A axis might play a role in different biological contexts, with a potential high interest in ageing-associated diseases, such as cancer and neurodegeneration." (PMID 30530920, 2018). "Pan-cancer analysis has revealed that cuproptosis related genes, such as ATP7B, ATP7A, and CDKN2A, harbor high-frequency mutations or abnormal expression patterns in various types of cancer." (PMID 40406488, 2025). "Platinum-based compounds can enter cancer cells by passive diffusion or CTR1-mediated import and can be exported by ATPase copper-transporting alpha/beta (ATP7A/7B) and multidrug resistance-associated protein 2/4 (MRP2/4)." (PMID 38727322, 2024). "We started by characterizing the basal level of Cu-dependent proteins which are reported to play a role in cancer development and spreading (i.e., ATP7A, LOXL2, CCS and Cytochrome c Oxidase) in the cells under study." (PMID 36454513, 2023). "It is noteworthy ATP7A or ATP7B can bind to platinum drugs to expel it from cancer cells, producing chemotherapy drug resistance." (PMID 36925927, 2023). "It has been reported that the mutations in DNA2, ACO2, and ATP7A were correlated with the initiation or poor clinical outcomes of cancers." (PMID 36685880, 2022). "In contrast to other CGRs, ATP7B, NLRP3, and ATP7A were distinctly hypomethylated in multiple cancers, such as BRCA, LUSC, and LUAD." (PMID 36387247, 2022). "The results showed that ATP7A and CRG_score, which were high in the C1 group, were consistent with the enrichment of signaling pathways in most cancers." (PMID 35979353, 2022). "Here, using a cell-surface proteomics approach, KRAS-mutated colorectal cancer cells are shown to express high levels of the copper transporter ATP7A, which has an essential roles in cancer cell survival and proliferation." (PMID 32709883, 2020). "Additional evidences implicated ATP7A and ATP7B were found to be overexpressed in some cancer cells with acquired cisplatin resistance." (PMID 32508020, 2020). "As we know, ATP7A is correlated with cisplatin resistance in different cancers, and similar to ATP7A, ATP7B mediates resistance to cisplatin in various tumors." (PMID 32508020, 2020). "We previously reported that ATP7B is involved in cisplatin resistance and ATP7A confers multidrug resistance (MDR) in cancer cells." (PMID 26988911, 2016). "Increased protein levels of ATP7A or ATP7B (both are copper export pumps) were reported to correlate to cisplatin resistance a in several human cancer cell lines examined." (PMID 27806319, 2016). "In this study, we show that ATP7B confers MDR to cancer cells, similarly to ATP7A, by facilitating nuclear efflux and following late endosome drug sequestration." (PMID 26988911, 2016). "That means ATP7A confers multidrug resistance (MDR) of cancer cells and related to drug resistance in clinical cancer cells." (PMID 26988911, 2016). "Cisplatin, a platinum-containing anti-cancer drug, binds to copper sites of ATP7A and ATP7B, and undergoes vectorial displacement in analogy with copper." (PMID 25242165, 2014).
cancer (continued). "Furthermore, TM can counteract chemotherapy resistance, which some cancer cells develop through increased expression of copper transport proteins (e.g., ATP7A and ATP7B)." (PMID 40406488, 2025). "For example, high expression of ATP7A in invasive breast cancer cells suggests that Cu‐ATPases may be involved in the metastasis process of cancer." (PMID 39267265, 2024). "Interestingly, elesclomol stimulated the degradation of the copper transporter ATP7A in intestinal cancer cells and increased the concentration of copper in cancer mitochondria." (PMID 39068453, 2024). "Although the mechanism of ATP7A/B signaling in tumors remains unclear, the transporter was indicated as a potential anti-cancer target and/or therapy response marker." (PMID 39068453, 2024). "ATP7A was also positively correlated with most cancer immune cells and immune checkpoints." (PMID 37885090, 2023). "Moreover, compared with other CGRs, ATP7B, NLRP3, and ATP7A are significantly hypomethylated in various cancers, such as BRCA, LUSC, and LUAD." (PMID 36387247, 2022). "Furthermore, it has been reported that ATP7A is related to the resistance of platinum-based chemotherapy in various kinds of cancers, such as CRC and breast cancer." (PMID 35265524, 2022). "Thus, closing this gap in understanding ATP7A/B function in malignant cells will open new opportunities for the development and improvement of anti-cancer therapeutic strategies." (PMID 31540259, 2019). "In order to better understand the clinical relevance of p73-dependent regulation of ATP7A in human cancer, we evaluated by computational webtools the impact of the correlation between p73 and ATP7A in different publicly available datasets of expression profiling of oncologic patients." (PMID 30530920, 2018). "Our computational analysis of expression profiling datasets of human cancer highlighted a potential correlation of TAp73/ATP7A with cancer pathogenesis; further studies will determine if this is a simple correlative connection, or an actual causative relationship." (PMID 30530920, 2018). "Our finding might delineate the possible underlining mechanisms of different ageing-related conditions, such as cancer and neurodegeneration, where alterations of the TAp73/ATP7A axis might play a direct impact." (PMID 30530920, 2018). "Despite a role in human cancer of ATP7A has been identified in drug-resistance (drug extrusion from cancer cells), our data indicate that high level of ATP7A is a positive prognostic factor, which becomes even stronger when concurrent with high TAp73 expression." (PMID 30530920, 2018). "Correspondingly, SOD3 (ρ=-0.36, p < 0.001) showed the strongest negative correlation with Cu abundance within this pathway, suggesting that elevated Cu levels may drive downregulation of this protective gene through upregulation of ATP7A, further promoting cancer aggressiveness." (PMID 41042257, 2025). "The cuproptosis inhibitory genes, ATP7B and ATP7A, as well as the remaining cuproptosis promoting CuRGs, are highly heterogeneous in tumors but tend to be lowly expressed, which may suggest a lower activation level of cuproptosis in cancer patients." (PMID 38573998, 2024). "Moreover, ATP7A is also involved in tumorigenesis and cancer drug resistance." (PMID 34390123, 2021). "The correlation between Cu metabolism and cell resistance to Pt drugs led to the idea that modulating the activity of Cu transporters, including ATP7A/B, might be explored to counteract drug resistance and, therefore, to improve the efficacy of platinum-based cancer therapy." (PMID 31540259, 2019). "The copper transporters ATP7A and ATP7B primarily mediate drug resistance in cancer cells via two distinct mechanisms." (PMID 40406488, 2025). "The critical link between Cu homeostasis and cancer is perhaps further illustrated by the frequent overexpression of ATP7A and ATP7B in invasive and drug-resistant cancers." (PMID 41304721, 2025).